CDH2 (cadherin 2)
Description:
Calcium-dependent cell adhesion protein; preferentially mediates homotypic cell-cell adhesion by dimerization with a CDH2 chain from another cell. Cadherins may thus contribute to the sorting of heterogeneous cell types. Acts as a regulator of neural stem cells quiescence by mediating anchorage of neural stem cells to ependymocytes in the adult subependymal zone: upon cleavage by MMP24, CDH2-mediated anchorage is affected, leading to modulate neural stem cell quiescence. Plays a role in cell-to-cell junction formation between pancreatic beta cells and neural crest stem (NCS) cells, promoting the formation of processes by NCS cells (By similarity). Required for proper neurite branching. Required for pre- and postsynaptic organization (By similarity). CDH2 may be involved in neuronal recognition mechanism. In hippocampal neurons, may regulate dendritic spine density. May promote axon outgrowth and motor fiber repair via DSP-mediated recruitment to outgrowth tips (By similarity).
Synonyms: CD325; CDHN; NCAD; ACOGS; ADHD8; ARVD14; CDw325
Tractability: Antibody: UniProt places it where antibodies can reach, with high confidence; its Gene Ontology location is reachable by antibodies, with high confidence; UniProt predicts a signal peptide or a membrane-spanning region; the Human Protein Atlas places it where antibodies can reach. PROTAC: ubiquitination databases record sites on it; its protein half-life has been measured; a small molecule that binds it is known.
Target class: Adhesion
Gene: Protein-coding gene on chromosome 18 (27,932,879 to 28,177,946, reverse strand). Ensembl gene ENSG00000170558.
Subcellular location: Cell membrane; Cell membrane, sarcolemma; Cell junction; Cell surface; Cell junction, desmosome; Cell junction, adherens junction; Cell projection, axon
Subcellular location (Human Protein Atlas): Plasma membrane; Cell Junctions
Pathways (Reactome):
Developmental Biology: Myogenesis; Regulation of MITF-M-dependent genes involved in extracellular matrix, focal adhesion and epithelial-to-mesenchymal transition
Metabolism of proteins: Post-translational protein phosphorylation; Regulation of Insulin-like Growth Factor (IGF) transport and uptake by Insulin-like Growth Factor Binding Proteins (IGFBPs)
Cell-Cell communication: Adherens junctions interactions
Gene Ontology:
Molecular function: alpha-catenin binding; beta-catenin binding; gamma-catenin binding; protein binding; cadherin binding; calcium ion binding; enzyme binding; identical protein binding; protein kinase binding; protein phosphatase binding; RNA binding
Biological process: cell-cell adhesion; adherens junction organization; calcium-dependent cell-cell adhesion; cell adhesion; cell migration; cell morphogenesis; cell-cell adhesion mediated by cadherin; cell-cell junction assembly; detection of muscle stretch; glial cell differentiation; neural crest cell development; neuronal stem cell population maintenance; positive regulation of axon extension; positive regulation of protein localization; synapse assembly; synaptic vesicle clustering; type B pancreatic cell development; homophilic cell-cell adhesion; neuroligin clustering involved in postsynaptic membrane assembly; positive regulation of synaptic vesicle clustering; regulation of postsynaptic density protein 95 clustering
Cellular component: adherens junction; anchoring junction; catenin complex; cell junction; cell-cell junction; cortical actin cytoskeleton; cytoplasm; extracellular matrix; focal adhesion; lamellipodium; plasma membrane; apical part of cell; axon; cell surface; desmosome; endoplasmic reticulum lumen; intercalated disc; neuron projection; apical plasma membrane; apicolateral plasma membrane; basolateral plasma membrane; fascia adherens; membrane; plasma membrane raft; presynapse; and 2 more
Genetic constraint (gnomAD): Loss-of-function variants: 13 observed, 61.5 expected, observed/expected ratio (o/e) 0.21, 90% interval 0.14 to 0.34. The upper end of that interval is the gene's LOEUF score, 0.34, which puts it in group 1 of 6, group 1 being the genes least tolerant of losing a copy. Missense variants: 700 observed, 940.92 expected, observed/expected ratio (o/e) 0.74, 90% interval 0.7 to 0.79. Synonymous variants: 356 observed, 356.69 expected, observed/expected ratio (o/e) 1, 90% interval 0.91 to 1.09.
Gene-disease validity (ClinGen):
ClinGen rates the evidence that CDH2 causes each of these diseases.
arrhythmogenic right ventricular cardiomyopathy (autosomal dominant): Limited.
dilated cardiomyopathy (autosomal dominant): Limited. Cardiomyopathy which is characterized by dilation and contractile dysfunction of the left and right ventricles.
Homologues: Orthologues: macaque CDH2 (99% identical), chimpanzee CDH2 (98% identical), guinea pig CDH2 (98% identical), pig CDH2 (98% identical), mouse Cdh2 (97% identical), rat Cdh2 (97% identical), rabbit CDH2 (91% identical), tropical clawed frog cdh2 (79% identical), zebrafish cdh2 (70% identical). Paralogues in human: CDH4 (66% identical), CDH1 (46% identical), CDH3 (40% identical), CDH15 (36% identical), CDH11 (32% identical), CDH13 (32% identical), CDH7 (32% identical), CDH6 (32% identical), CDH10 (31% identical), CDH9 (31% identical), CDH8 (31% identical), CDH12 (30% identical), and 21 more.
Diseases named in the same sentence as CDH2 in open-access papers:
CDH2 is named in the same sentence as 386 diseases in open-access papers, as found by Europe PMC text mining. Sharing a sentence is not in itself a finding about the gene and the disease. The quoted sentences say what the papers report.
breast cancer (449 papers, 2003 to 2026). A primary or metastatic malignant neoplasm involving the breast. "We found that CDH2, 4, 6, and 17 were frequently amplified/overexpressed in breast cancer while CDH1 was downregulated/mutated." (PMID 28392805, 2017). "We next assessed if the gene expression changes in CDH1 and CDH2 induced by ALDH1A3 in the breast cancer cells translate to protein changes in the cells." (PMID 39251846, 2024). "aCT1 bound to BTF3 in our proteomic analysis and consistent with this, the gene that encodes N-cadherin, CDH2, was significantly reduced in aCT1-treated samples in our gene expression analysis using the NanoString nCounter Breast Cancer 360 panel." (PMID 38275864, 2024). "In contrast, the HS578T-Hyg breast cancer cells are in a M state due to the expression of “classical” M markers, such as CDH2, VIM, ZEB1 and WNT5A." (PMID 38139138, 2023). "It has been reported that BHLHE40 can promote SNAI1 and SNAI2 expression and inhibit the expression of CLDN1, CLDN4, and CDH2 in breast cancer, promoting the migration and invasion of tumor cells." (PMID 37377917, 2023). "The accumulation of nucleolin at the cell leading edge or protrusions was able to interact with CDH2 mRNA to stabilize the mRNA and enhance its local translation to promote breast cancer cell invasion." (PMID 37958584, 2023). "In breast tumors, CDH2 expression is correlated with invasion through CDH2-mediated interactions between breast cancer cells and stromal cells." (PMID 37958584, 2023). "In this study, we reveal a novel function of lncRNA SNHG15 in mediating breast cancer cell invasion through regulating the local translation of CDH2 mRNA." (PMID 37958584, 2023). "MiR-708 downregulation in different breast cancer cell lines causes an increase in the expression of three of its direct targets, Zinc Finger E-Box Binding Homeobox 1 (ZEB1), Cadherin 2 (CDH2), and vimentin, which are known EMT inducers." (PMID 35011736, 2022). "CDH2 was correlated with upregulated motility and invasion in human breast epithelial and breast carcinoma cell lines." (PMID 36013233, 2022). "CDH2 is required for connexin 43 (Cx43)–mediated gap junction intercellular communication between breast cancer cells and bone marrow niche cells to achieve dormancy and chemoresistance." (PMID 34078741, 2021). "Loss of the epithelial marker E-cadherin and acquisition of mesenchymal markers (e.g., vimentin, N-cadherin/CDH2 and fibronectin) are associated with a poor prognosis in different types of solid cancers, including prostate, bladder and breast cancers." (PMID 33567533, 2021). "CDH2 is a predictive biomarker for distant metastasis in early-stage breast cancer, that is commonly detected in breast cancer cells and provides a mechanism for transendothelial migration." (PMID 32909943, 2020). "Our results have shown that different EMT phenotypes of CTCs (epithelial, epithelial-mesenchymal and mesenchymal) can be distinguished in CTCs-EBF of early breast cancer using a panel of 7 genes (MGB1/HER2/CK19/CDH1/CDH2/VIM/PLS3) tested in qPCR." (PMID 30634453, 2019). "To confirm the interaction between LINC00536, CDH2, and mir‐204 in the ceRNA network in breast cancer cells, we detected the expression levels of mir‐204 and CDH2 in LINC00536‐siRNA1 breast cancer cells." (PMID 30932362, 2019). "Using GraphPad Prism to analyze the expression levels of LINC00536, CDH2, and mir‐204, the results indicated that the expression levels of LINC00536 and CDH2 were increased in breast cancer, while mir‐204 expression was decreased." (PMID 30932362, 2019). "Only one (CDH2) of the 13 EMT-related genes exhibited significantly higher gene expression in the Brain meta compared to the Primary breast cancers group (P < 0.001)." (PMID 31527824, 2019). "BRC-31 breast cancer cells expressed high levels of cdh2, fn1 and vim and low levels of cdh1 and krt-8 compared to BRC-17, 32, 36 and 196 cells." (PMID 29382358, 2018).
breast cancer (continued). "It has been reported that knockdown of TRIM29 in breast cancer cells was sufficient to induce EMT with increased level of CDH2 and VIM and decreased level of CDH1 via suppression of TWIST." (PMID 29228692, 2017). "As previously reported, CDH2 was often upregulated in cancers including breast cancers and acts as a promoting factor of cancer invasion and metastasis." (PMID 28392805, 2017). "The expression of EMT markers, including CDH1, CDH2, VIM, ZEB1 and ZEB2, is associated with poor prognosis of breast cancer patients." (PMID 26062653, 2015). "Both in mouse mammary tumors and in human breast cancers, we observed elevation of Vim, Cdh2 (N-cadherin), Snai1 and Twist1 and downregulation of Cdh1 (E-cadherin) and Ocln." (PMID 25217618, 2014). "KLF6-SV1, one of these splice variants, is able to drive breast cancer cells into an EMT-like phenotype, with loss of CDH1 and increased expression of CDH2 and FN1." (PMID 24429391, 2014). "Our results have shown the expressional association and clinical relevance of six genes (CDH2, FN1, CITED2, CTNNB1, and CTNNA3) together with GRHL2 for breast cancer metastases." (PMID 23441166, 2013). "Reduction of CDH1 is often accompanied by reciprocally increased expression of CDH2, and indeed CDH2 has been shown to promote breast cancer cell invasiveness in various studies." (PMID 19636430, 2009). "Notably, N-cadherin (N-Cad, encoded by the CDH2 gene), an EMT marker recognized as being critical for the diagnosis and prognosis of breast cancer, was upregulated in this study." (PMID 38711026, 2024). "Notably, Sparc, Spp1, and Cdh2 were found to be upregulated in the human breast cancer samples included in TCGA database, consistent with the clinical relevance of Mbd2-regulated genes in breast cancer." (PMID 38556549, 2024). "CDH2 has been confirmed to be up-regulated in breast cancer, prostate cancer, and melanoma." (PMID 37531206, 2023). "Moreover, the upregulation of FN1, CDH2, and VIM is commonly associated with the epithelial–mesenchymal transition (EMT) in breast cancer and also in mammary epithelial cells." (PMID 36013233, 2022). "In particular, heterotypic adherens junctions between breast cancer cell-derived CDH1 and CDH2 in an osteogenic niche can support bone colonization of circulating breast cancer cells and stimulate the mechanistic target of rapamycin (mTOR) pathway-driven micrometastasis formation." (PMID 34831167, 2021). "CDH2 (encoding N-cadherin), VIM (encoding vimentin), TWIST1/2 (products which are EMT transcriptional factors) and SNAI1, as well as ZEB1, are well known key players involved in EMT-like processes of breast cancers." (PMID 27617643, 2016). "The invasiveness of breast cancer cells depends on the activity of transcription factors that modulate the expression of cell adhesion proteins, such as E-cadherin, encoded by the CDH1 gene and N-cadherin, encoded by the CDH2 gene, and the epithelial-to-mesenchymal transition." (PMID 35163478, 2022). "Overall, almost all the EMT genes analyzed were downregulated in breast cancer samples compared to normal breast tissues, except for CDH1, CTNNB1, and CDH2 that were upregulated in BC." (PMID 32911851, 2020). "When we focused on the 68 breast cancer cell lines from the DepMap dataset, we measured increased correlation of VIM expression with CDH2 (R2 = 0.5)." (PMID 40833805, 2025). "In breast cancer cells, miR-708-3p inhibits EMT by directly targeting ZEB1, cadherin 2, and vimentin." (PMID 38920689, 2024). "Among five subtypes of human breast tumors, the expression levels of TWIST1 and its upregulated genes, Vim and SNAI2, are the highest, while its repressed target genes, CDH2 and ESR1, are the lowest in ER−/HER2− breast cancers." (PMID 38893094, 2024). "As a cancer suppressor miRNA, it completely inhibits breast cancer metastasis and chemotherapy resistance by regulating MT (directly targeting EMT activators, such as ZEB1, CDH2, and vimentin)." (PMID 37809692, 2023).
breast cancer (continued). "Next, we used this technology to knock out Cdh2 in the Cas9- and EGFP-stably expressed 4T1 breast cancer cells." (PMID 35890278, 2022). "In osteoblasts, which are involved in osteolytic breast cancer metastasis, MZF1 has been shown to upregulate the expression of another EMT regulator, N-cadherin (CDH2)." (PMID 31963147, 2020). "In order to determine the variation, we have compared the level of general breast cancer markers (MGB1, HER2) and genes used for CTCs-EBF classification into EMT phenotypes (CK19, CDH1, VIM, CDH2, PLS3)." (PMID 30634453, 2019). "Pearson's correlation analysis run on 226 samples made up of 56 breast cancer cells showed that the FRK transcript levels negatively correlated with the transcript levels of VIM, CDH2, and TWIST1, with R-values of -0.28; -0.20; -0.25 respectively (P<0.001)." (PMID 29348886, 2017). "We found that both COX-2 expression and activity concomitantly modulated TGFβ-promoted breast cancer cells stemness and expression of FN1, CDH2 and KRT14." (PMID 28054666, 2017). "The EPCAM-positive breast-cancer cells and colon-cancer cells expressed EPCAM on all 96 h, whereas they only expressed KRT19 and CDH2 from 0 to 72 h." (PMID 28975085, 2017). "We found that the mean transcript expression of VIM, CDH2, FN1, and TWIST1 were higher in the basal B breast cancer cells with low FRK transcript levels as compared to Basal A and Luminal cells that harbor high FRK transcript levels (P<0.05)." (PMID 29348886, 2017). "Training on public gene expression profiles of 995 breast cancer patients, this method prioritized one gene-set pair (GRHL2, CDH2, FN1, CITED2, MKI67 versus CTNNB1 and CTNNA3) from all 2717 possible gene-set pairs (GSPs)." (PMID 23441166, 2013). "Moreover, changes in the promoter methylation status of the Cdh2 and Spp1 genes, as a direct or indirect effect of Mbd2 deletion and subsequent binding by a transcriptional repressor, may also constitute a possible mechanism for regulating these genes in breast cancer." (PMID 38556549, 2024). "CDH2 staining intensities were negative (nine cases), weak (three cases), and strong (one case) in breast cancer samples." (PMID 36315446, 2022). "CDH1, CDH2, and CDH12 exhibited strong intensities in cell nuclei in breast cancer samples." (PMID 36315446, 2022). "Particularly, the negative association between the genes CDH2, CDH3, CDH11, CDH13, CDH18 and NAT1 N-acetylation activity supports observations of high NAT1 expression in breast cancer and increased metastasis." (PMID 35046826, 2021). "N-cadherin (CDH2), a direct target of miR-145, is a cell-cell adhesion molecule that contributes to the invasive/metastatic phenotype in many cancers such as gastric cancer, breast cancer, and lung cancer." (PMID 33005184, 2020). "Quantitative real-time PCR analyses of EMT genes TWIST1, Snail1, Snail2 and CDH2 in monocultured and ASCs co-cultured MCF-7 and MDA-MB-231 revealed that most of these EMT signature genes were downregulated in co-cultured breast cancer cells." (PMID 33271950, 2020). "The regulation of N-CADHERIN (CDH2) by SOX11 is significant since CDH2 promotes motility in human breast cancer cells regardless of their E-CADHERIN expression." (PMID 32909943, 2020). "Expression of VIM, CDH1, CDH2, PLS3, CXCR4, CD44 and NANOG have been found in healthy controls and the maximal expression levels of these genes were the threshold beyond which CTCs-EBF of breast cancer patients were considered positive." (PMID 30634453, 2019). "For instance, CDH2 promotes cell motility in breast cancer cells regardless of the expression of CDH1." (PMID 28392805, 2017). "Thus, CDH2 and VIM are both bona fide markers of breast cancer EMT." (PMID 34831167, 2021). "Interestingly, CTCs-negative breast cancer samples had increased level of CDH2 in comparison to CTCs-positive samples (average expression 31.31 vs. 19.53, respectively; p = 0.020)." (PMID 30634453, 2019).